ZNF391 (zinc finger protein 391)
Description:
May be involved in transcriptional regulation.
Synonyms: dJ153G14.3
Tractability: PROTAC: ubiquitination databases record sites on it.
Gene: Protein-coding gene on chromosome 6 (27,374,615 to 27,405,026, forward strand). Ensembl gene ENSG00000124613.
Subcellular location: Nucleus
Gene Ontology:
Molecular function: DNA-binding transcription factor activity, RNA polymerase II-specific; RNA polymerase II transcription regulatory region sequence-specific DNA binding
Biological process: regulation of transcription by RNA polymerase II
Cellular component: nucleus
Genetic constraint (gnomAD): Loss-of-function variants: 1 observed, 2.25 expected, observed/expected ratio (o/e) 0.44, 90% interval 0.15 to 1.68. That is too few expected variants to judge how well the gene tolerates losing a copy. Missense variants: 375 observed, 449.31 expected, observed/expected ratio (o/e) 0.83, 90% interval 0.77 to 0.91. Synonymous variants: 126 observed, 149.42 expected, observed/expected ratio (o/e) 0.84, 90% interval 0.73 to 0.98.
Homologues: Orthologues: chimpanzee ZNF391 (99% identical), macaque ZNF391 (94% identical), pig ZNF391 (76% identical), dog ZNF391 (70% identical). Paralogues in human: ZNF135 (50% identical), ZFP2 (48% identical), ZNF250 (48% identical), ZNF892 (48% identical), ZNF606 (47% identical), ZFP3 (47% identical), ZNF623 (47% identical), ZNF3 (46% identical), ZNF189 (46% identical), ZNF699 (46% identical), ZNF7 (46% identical), ZNF879 (46% identical), and 164 more.
Diseases named in the same sentence as ZNF391 in open-access papers:
ZNF391 is named in the same sentence as 2 diseases in open-access papers, as found by Europe PMC text mining. Sharing a sentence is not in itself a finding about the gene and the disease. The quoted sentences say what the papers report.
cancer (1 paper, 2024). A tumor composed of atypical neoplastic, often pleomorphic cells that invade other tissues. "Consequently, we conducted a pan-cancer analysis of gene promoter methylation and observed significant associations between several genes, including ZNF323, ZSCAN23, SCAND3, PRSS16, ZNF391, NKAPL, and ZNF311, and promoter methylation." (PMID 38495498, 2024).
ZNF391 also shares sentences with these, for which no sentence is quoted: rheumatoid arthritis (1 paper).